CTLA4 (cytotoxic T-lymphocyte associated protein 4)
Diseases named in the same sentence as CTLA4 in open-access papers (continued):
Sharing a sentence is not in itself a finding about the gene and the disease.
cancer (continued). "It has been reported that anti-CTLA-4 monotherapy produces durable responses in many cancers, mainly in melanoma." (PMID 36713558, 2022). "Immune checkpoint inhibition has in many ways revolutionized cancer therapy by blocking primarily the inhibitory molecules, PD-1 or CTLA-4, that are expressed by exhausted effector T cells or Treg cells." (PMID 36591229, 2022). "The HIF-1α inhibitor echinomycin potentiated the cancer immunotherapeutic effects of anti–CTLA-4 therapy, with efficacy comparable to that of anti–CTLA-4 plus anti–PD-1 antibodies." (PMID 35239514, 2022). "ICI therapy represented by PD-1, PD-L1 and CTLA-4 inhibitors has undoubtedly achieved encouraging progress in the therapeutic landscape of cancer." (PMID 35093128, 2022). "Immune checkpoint molecules such as CTLA-4, PD-1, and PD-L1 have been validated as targets in cancer immunotherapy, but few studies have explored their roles in cancer prognosis." (PMID 35769504, 2022). "The discovery that it was possible to relieve the brake of TIL suppression with immune checkpoint inhibitors (ICI) targeting CTLA4, PD-1, and PD-L1 has revolutionized the treatment of cancer." (PMID 35681548, 2022). "Over the past decade, immunotherapy has revolutionized cancer treatment, mainly by immune checkpoint inhibitors, such as nivolumab (anti-PD1) and ipilimumab (anti-CTLA4), but also by adoptive immune cell therapies and therapeutic cancer vaccines." (PMID 35681575, 2022). "The combination of CTLA-4 and PD-1 blockers increases the response rates in patients, and ipilimumab (anti-CTLA-4) plus nivolumab (anti-PD-1) in combination are particularly effective in different cancer types, such as those affecting the kidney." (PMID 35269781, 2022). "The main immune checkpoints that have been successfully targeted in cancer treatments are PD-1, its ligand PD-L1, and cytotoxic T-lymphocyte antigen 4 (CTLA-4)." (PMID 35078492, 2022). "Immune checkpoints, such as PD-1 and its ligand PD-L1, and CTLA-4 inhibitors work by altering the interaction immune system/cancer cells." (PMID 35628540, 2022). "For example, activated T cells expressing CTLA-4 and PD-1 develop immunological tolerance to cancer cells in a resorbable area." (PMID 36276117, 2022). "Systemic administration of CPIs, anti-PD-1 and anti-CTLA-4 antibodies, is the standard regimen for cancer immunotherapy." (PMID 35136110, 2022). "Immune checkpoint inhibitors (ICIs) to programmed cell death protein 1 (PD-1), programmed death-ligand 1 (PD-L1), and cytotoxic T lymphocyte-associated antigen-4 (CTLA-4) can activate antitumor immunity and mediate cancer recession." (PMID 35535221, 2022). "Anti-PD-1 therapy is expected to activate the immune system’s effector reaction at the level of cancer cells, whereas anti-CTLA-4 therapy is thought to stimulate T cells." (PMID 36016257, 2022). "Checkpoint inhibitors that disrupt the function of Tregs via blocking inhibitory PD-1 and CTLA-4 have shown efficacy in the treatment of cancers." (PMID 35704583, 2022). "Cancer immunotherapy has achieved a great accomplishment with the approval of PD-1/L1 and CTLA-4 inhibitors in the clinical care of a growing list of cancer types." (PMID 35173722, 2022). "Growing evidence suggests that combining USP7 inhibitors with immunotherapies such as anti-PD1 or anti-CTLA4 antibodies, and cancer vaccines has the potential to significantly increase antitumor immune responses." (PMID 36428632, 2022). "ICI drugs target the co-inhibitory receptors present on T cells, such as cytotoxic T lymphocyte-associated protein-4 (CTLA-4) and programmed cell death-1 (PD-1) or their ligand (PD-L1) expressed on cancer cells, by selectively blocking their interaction." (PMID 36556139, 2022). "Cancer immunotherapy targeting CTLA4, PD-L1, or PD-1 has become a widely used method of treating various types of cancer." (PMID 36091162, 2022). "CTLA-4 and PD-1 are negative regulators of T-cell activity that limits immune responses against cancer." (PMID 35428347, 2022).
cancer (continued). "The therapeutic targeting of immune checkpoints has attracted considerable attention in cancer immunotherapy, particularly concerning CTLA-4 and programmed cell death 1 (PD-1)." (PMID 35893056, 2022). "When attached to protein B7 on a cancer cell, CTLA-4 prevents T cells from killing cancer cells, deactivating the T cells." (PMID 35884596, 2022). "As a checkpoint immunotherapies targets, the CTLA4 has shown remarkable success in the treatment of certain cancer types." (PMID 35067176, 2022). "The TIMER2.0 method was used to analyze the correlation between the expression of PD-1, PD-L1, and CTLA-4 in pan-cancer, and it was detected that PD-1/PD-L1/CTLA-4 had a statistical correlation in pan-cancer (p < 0.05)." (PMID 36147250, 2022). "Another “brake” on immune cells that negatively regulates activation of T-cells (CD4+ and CD8+) is cytotoxic T-lymphocyte-associated protein 4 (CTLA-4); the antibody ipilimumab inhibits CTLA-4 function and is also used to treat cancer." (PMID 36215234, 2022). "Studies have shown that immune checkpoints such as immunosuppressants PD-1 and CTLA4 show important value in inhibiting the occurrence and development of a variety of malignant tumors." (PMID 36313456, 2022). "Immunotherapy targeting checkpoint inhibitors, such as CTLA-4 and/or PD-1, has emerged as a leading cancer therapy." (PMID 35621582, 2022). "The importance of this CTLA‐4 molecule in antitumor immune responses has recently been highlighted by the success of anti‐CTLA‐4 monoclonal antibodies (mAbs), including ipilimumab, as cancer immunotherapy." (PMID 35435327, 2022). "It is widely acknowledged that the upregulation of PD-L1 in cancer cells or upregulation of PD-1 or CTLA4 results in the immunosuppressive environment in TIME." (PMID 36262348, 2022). "Antibody-based therapies targeting CTLA-4 and PD-1 have achieved lasting responses in some patients against a range of cancer types." (PMID 35910232, 2022). "Since anti-CTLA-4 antibodies are used to treat cancer, it is tempting to suspect that treatment of RA with Abatacept would increase the risk of developing malignancy." (PMID 35784333, 2022). "The combination of anti-PD-1 and anti-CTLA-4‐agents further improves clinical response rates compared with single‐agent activities in some types of cancers." (PMID 36121543, 2022). "By downregulating CSN5, curcumin enhances the sensitivity of cancer to anti-CTLA-4 treatment and the function of antitumor T cells by downregulating PD-L1 expression, thus alleviating cancer growth." (PMID 35279217, 2022). "The application of immune checkpoint inhibitor (ICI) therapy targeting PD-1, PD-L1, or CTLA-4 represents a major breakthrough for many types of cancers, including HCC." (PMID 36110210, 2022). "The discovery of T-cell-negative regulation by CTLA-4 was a spark to the establishment of CTLA-4 blockade as a form of cancer immunotherapy." (PMID 36648843, 2022). "ICBs such as anti-CTLA-4 and anti-PD-1/L1 induce unprecedented clinical benefits in patients with various types of advanced cancer and are revolutionizing the field of cancer treatment." (PMID 36008408, 2022). "Two such immune checkpoints, PD-1/PD-L1 and CTLA-4, have so far received the most attention in cancer immunotherapy." (PMID 35585975, 2022). "Three immune checkpoint regulators, namely CTLA-4, PD-1, and PD-L1 have gained enormous attention in the oncology field as promising potent targets for cancer therapeutics." (PMID 35337133, 2022). "Immunotherapies targeting the T-cell immune inhibitory receptors, cytotoxic T-lymphocyte-associated antigen-4 (CTLA4) and programmed cell death-1 (PD1), have transformed clinical management of patients with a range of advanced cancers." (PMID 36230753, 2022). "In another study, anti-CTLA4 enhanced the treatment outcome of a therapeutic cancer vaccine through the improvement of T cell priming in the lymphoid tissues." (PMID 35017664, 2022).
cancer (continued). "Despite its toxicity, anti-CTLA-4 has regained interest in recent years due to its unique immunological activity in hard-to-treat cancers, especially as a combination agent with anti-PD-1." (PMID 35326731, 2022). "Anti-programmed cell death 1 (PD-1) and anti-cytotoxic T-lymphocyte-associated protein 4 (CTLA4) checkpoint inhibitors have known efficacy in MSI-H cancers, as well as TMB-high cancers." (PMID 35267592, 2022). "The stimulation of PD-L1, PD-1, and CTLA-4 proteins on T cells impedes the recognition of cancer cells and prevents their elimination." (PMID 35743107, 2022). "CTLA-4 and PD-1 co-inhibitory receptors on T cells, as well as their ligands produced by cancer cells, are the targets of immune checkpoint inhibitors (ICIs)." (PMID 35744922, 2022). "Cancers can elude immune response by exploiting immune checkpoint genes such as PD-1/PD-L1 and CTLA-4." (PMID 36160408, 2022). "Immunotherapy represented by anti-PD-1 and anti-CTLA4 has become one of the promising options for cancer treatment." (PMID 36147441, 2022). "IDO1, in combination with other immunotherapeutics such as PD-1/PD-L1 or CTLA-4 inhibitors, has an objective response rate that varies between 10% and 57% in different cancer types." (PMID 35903691, 2022). "Preclinical studies have suggested that the combination of anti-PD-1 or anti-PD-L1 and antibodies against CTLA-4 is a promising treatment strategy for advanced cancers." (PMID 36248841, 2022). "ICIs such as PD-1/PD-L1 or cytotoxic T-lymphocyte (CTLA-4) can produce robust and durable response in several cancer patients, including advanced HCC." (PMID 35986302, 2022). "CTLA-4 represents one of the first IC studied that is neo-expressed in many adult and pediatric cancers or with increased expression in different tumors, mostly correlated with HLA-G and PD-L1/L2." (PMID 35328349, 2022). "Immune checkpoint inhibitors, namely anti-CTLA-4, anti-PD-1 and anti-PD-L1 monoclonal antibodies, have emerged in the last decade as a novel form of cancer treatment, promoting increased survival in patients." (PMID 36204105, 2022). "Recent study reports that metformin increases cytotoxic T lymphocyte (CTL) activity against cancer cells, and the combination of metformin and CTLA4 blockade increases the efficacy of immunotherapy." (PMID 36033393, 2022). "The intracellular domain of CTLA-4 is altered in cancer patients, while the surface expression is noticeably higher in cancer patients." (PMID 36423060, 2022). "The mechanism of action of CPI therapy is based upon blocking of inhibitory signals transmitted from cancer cells to infiltrating immune cells through the PD-L1 and CTLA-4 checkpoints, which are commonly upregulated in cancer cells." (PMID 36923311, 2022). "Targeting PD1/PD-L1 and CTLA-4/B7 with specific inhibitors has demonstrated exciting preclinical and clinical efficacy in several cancers." (PMID 36389798, 2022). "Ipilimumab is the single Food and Drug Administration (FDA)-approved ICI and the most prominent member of CTLA-4 inhibitor for cancer treatment." (PMID 36046747, 2022). "The critical role that CTLA-4 plays in suppressing the immune system is what led to it being the first immune checkpoint receptor targeted for cancer immunotherapy." (PMID 36389815, 2022). "CTLA-4 on T cells throughout the induction phase of an anti-cancer immune reaction obstructs T cell activation by inhibiting the formation of interaction between CD80/CD86 and CD28 and conveying inhibitory signals, directly suppressing T cell activation." (PMID 35392976, 2022). "For instance, the therapeutic effects of the blockade of PD-1/PDL-1 and CTLA-4 checkpoints have been adopted to treat various cancers." (PMID 35177112, 2022). "Clinical trials using monoclonal antibodies against HLA-G and other IC are currently ongoing with cancer patients where antibodies and inhibitors of PD-1 and CTLA-4 showed encouraging results." (PMID 35328349, 2022).
cancer (continued). "The 2018 Nobel Prize in physiology and medicine was awarded to James Allison and Tasuku Honjo for their breakthrough in cancer immunotherapy by targeting CTLA-4 and PD-1, respectively." (PMID 36480493, 2022). "In the last decade, therapeutics targeting immune checkpoint inhibitors (i.e., CTLA-4, PD-1, and PD-L1) have revolutionized cancer care for subsets of oncology patients." (PMID 35790753, 2022). "At the same time, anti-CTLA-4 plus anti-PD-1 combination therapy is currently in clinical trials in adjuvant and neoadjuvant settings for several cancers." (PMID 35326731, 2022). "Monoclonal antibodies targeting immune checkpoints CTLA‐4, PD‐1 and PD‐L1, referred to as immune checkpoint inhibitors (ICIs), have become a new standard of care in a wide range of cancers." (PMID 34270845, 2022). "ICIs block the immune escape of cancer cells by binding to CTLA-4, PD-1 or PD-L1, etc., thereby recovering the killing activity of T cells against cancer cells." (PMID 35647204, 2022). "Recently, immunotherapies represented by immune checkpoints, including PD-L1, PD-1, and CTLA-4, have undoubtedly emerged as a major breakthrough in cancer treatment." (PMID 35777046, 2022). "Cancer immunotherapy is gaining momentum following the recent success of antibodies targeting checkpoint molecules CTLA-4 and PD-1." (PMID 36142142, 2022). "PD-1, CTLA4, PD-L1 inhibitors currently are among the hottest ICIs, contribute much to treat cancers, including SKCM." (PMID 35345444, 2022). "CTLA-4, which is expressed widely on T cells as well as various other cells, including cancer cells, DCs25, and MDSCs26, is an immune checkpoint whose major role is attributed to the modulation of T cell priming, differentiation, and function." (PMID 35304456, 2022). "Cancer cells are also able to inhibit immune cells at a state of senescence or exhaustion through death receptors such as Fas or PD-1/CTLA-4/LAG-3, respectively." (PMID 35652109, 2022). "The use of CTLA4 as well as PD-L1 and PD-1 inhibitors can be seen as a major milestone in cancer therapy." (PMID 35630835, 2022). "In 2011, FDA approved CTLA-4 antibody (ipilimumab) to be applied in melanoma, which marked a new era of cancer immunotherapy." (PMID 35281059, 2022). "For example, Plasmodium and Toxoplasma strains expressed with particular ‘chimeric antigen receptor’, i.e., PD-1 or CTLA-4, so as to increase the targeting ability of cancer cells." (PMID 36004920, 2022). "Immune checkpoint inhibitor (ICI) therapy targeting the PD-1/PD-L1/CTLA-4 pathway has been approved for the treatment of more than 10 cancer types." (PMID 35252205, 2022). "Immunotherapies involving PD-1, PD-L1 and CTLA-4 blockade have undoubtedly emerged as a major breakthrough in cancer therapy." (PMID 35252205, 2022). "Therapeutic blockade of the immune checkpoint proteins programmed cell death protein 1 (PD-1) and cytotoxic T lymphocyte antigen 4 (CTLA4) has transformed cancer treatment." (PMID 35017553, 2022). "As the most important immunotherapy drugs, ICIs—mainly represented by anti‐CTLA4 and anti‐PD antibodies—have shown an unexpected antitumor activity and have improved the prognosis in various types of cancer." (PMID 34783061, 2022). "Immune checkpoint inhibitors (ICI) targeting cytotoxic T-lymphocyte-associated protein 4 (CTLA-4), programmed cell death protein 1 and its ligand (PD-1/PD-L1) have become the current standard-of-care for advanced cancers." (PMID 36419114, 2022). "It has also been illustrated that CD4+ CTLA-4+ T cells in circulation are considerably elevated in patients with advanced cancer stages." (PMID 35855850, 2022). "More clinical studies involving CTLA4 or PD-1 blockade are being evaluated for other types of cancer including mesothelioma, sarcoma and CRC." (PMID 35372044, 2022). "CTLA-4 is often upregulated in cancer patients and is therefore an attractive target to enhance T-cell antitumour activity." (PMID 35813830, 2022).
cancer (continued). "Anti-CTLA-4 therapy can confer long-lasting clinical benefits in cancer patients as a single agent or in combination with other immunotherapy agents." (PMID 35326731, 2022). "Discovery of immune checkpoint such as CTLA-4 and PD-1 plays an indispensable role in the development of cancer immunotherapy." (PMID 35651784, 2022). "The PD-L1 inhibitors and the CTLA-4 inhibitors increase the average life expectancy of cancer patients by passing through different cellular immune pathways." (PMID 36311703, 2022). "With the development of immunotherapy, PD-1/CTLA4 inhibitors have been widely used in clinical applications and improved prognosis of various cancers." (PMID 35432443, 2022). "Our results revealed that high LMS was positively associated with the expression of CTLA4, PDCD1, TIGIT and GZMB in the EC and pan-cancer cohorts." (PMID 35834061, 2022). "Recently, abnormal expression of CTLA-4 has been reported in numerous tumors and is believed to contribute to the initiation and progression of cancer." (PMID 35434132, 2022). "The analysis of cancer patient data revealed that high EMT score is associated with high expression of PD‐1, PD‐L1, CTLA4, OX40L, and PD‐L2 in several cancer types." (PMID 35575054, 2022). "Checkpoint blockades (anti-PD-1, anti-PD-L1, and CTLA-4) have reached remarkable success in many types of cancers." (PMID 35864548, 2022). "In recent years, immune checkpoint inhibitors with CTLA-4, PD-1 and PD-L1 monoclonal antibodies has become a successful treatment for several advanced cancers." (PMID 36313280, 2022). "For several cancers, blocking immune checkpoint signaling pathways such as the PD-1/PD-L1 axis and CTLA4 significantly improves survival." (PMID 36611806, 2022). "Combination therapy, where a PD-1/PD-L1 inhibitor is combined with a CTLA-4 inhibitor, has been proven to be more effective than monotherapies in some types of cancer, but an increase in the incidence of adverse events was observed." (PMID 35328510, 2022). "ICIs that target programmed cell death protein 1 (PD-1) and programmed cell death protein ligand 1 (PD-L1), as well as cytotoxic T lymphocyte antigen 4 (CTLA-4), have made significant advances in cancer treatment." (PMID 35999569, 2022). "Cancer vaccine formulation can dominantly determine synergy, or lack thereof, with CTLA-4 and PD-L1 checkpoint blockade therapy for cancer." (PMID 36059952, 2022). "Immunotherapy agents, such as anti-PD1, anti-PD-L1, and anti-CTLA4 antibodies, are increasingly being used in cancer treatment; however, only a subset of patients with HCC benefits from these therapies." (PMID 35572523, 2022). "In most cancer types, SERCA3 expression was also associated with immune checkpoints, including PDCD1 and CTLA-4." (PMID 36385955, 2022). "The discovery of immune checkpoint proteins such as PD-1/PDL-1 and CTLA-4 represents a significant breakthrough in the field of cancer immunotherapy." (PMID 35621637, 2022). "Antibodies targeting checkpoint molecules such as cytotoxic T-lymphocyte-associated protein 4 (CTLA-4) or programmed cell death protein-1 (PD-1) have been approved and are in clinical practice for the therapy of a variety of cancers." (PMID 35565343, 2022). "The complex CTLA-4/B7 blocks the anti-cancer activity of T1 and T8 cells, and at the same time it also increases the proliferation of Tr; we assume that this increase in Tr is caused by a change from T1 to Tr phenotype, as in the case of PD-1/PD-L1." (PMID 35015785, 2022). "Based on the efficacy of blocking CTLA-4 in mouse models, several drug antibodies against CTLA-4 have been used clinically and tested in trials for advanced cancers." (PMID 35585975, 2022). "In fact, ICs pathways, more importantly, PD-1/PD-L1 and CD28/CTLA-4, are co-opted by tumors, altering expression of proteins to ease cancer cells' evasion from immune surveillance as a result of the inhibiting T cell responses." (PMID 36510217, 2022).